FOXP3 (forkhead box P3)
Diseases named in the same sentence as FOXP3 in open-access papers (continued):
Sharing a sentence is not in itself a finding about the gene and the disease.
tumor (continued). "The corresponding cut-off values for CD8 in stroma and tumor region was 40 and 2%, while 1% for Foxp3 in both stroma and tumor region." (PMID 31138162, 2019). "IDO expression was positively correlated with tumor‐infiltrating Foxp3 + Tregs (P < .001) as well as DC2s (P < .001), whereas it was negatively correlated with the tumor‐infiltrating CD4/CD8 + T cell ratio (P = .023)." (PMID 31631566, 2019). "In the current study, 100 GC patients were divided into high or low tumor-infiltrating Treg groups according to the median number of intratumoral FoxP3+ Tregs as the cut-off value." (PMID 31417548, 2019). "Conversely, CD4+ FOXP3+ Th2 cells, M2 macrophages, and myeloid-derived suppressor cells (MDSCs) can drive tumour growth." (PMID 31527531, 2019). "Non-Treg cells in untreated SCC are an important source of IL-10, which is also produced by tumor FOXP3+ Treg cells." (PMID 30766448, 2019). "CD4+CD25+CD127dim/− Tregs express high level of transcriptional factor FoxP3 and secrete interleukin (IL)-35/IL-10, and suppress activation and expansion of tumor-antigen-specific effector T cells to maintain peripheral tolerance in malignant cancers." (PMID 30988066, 2019). "CCL20 assists tumor cells in immune evasion by increasing the migration of CD4+Foxp3+ Tregs towards tumor location." (PMID 31192256, 2019). "Studies have outlined the increased infiltration of FoxP3+ Treg cells in tumour and peripheral blood of HCC patients, their role in anti-tumour immunity and their aide in tumour progression." (PMID 30893948, 2019). "We analyzed the association between peripheral and tumor‐infiltrating T cells, DCs, IDO, and Foxp3 + Tregs in tumor tissues." (PMID 31631566, 2019). "The most upregulated of these proteins, FKBP1A, plays a role in T cell activation in FOXP3 expression and regulatory T cell suppression, in addition to promoting tumour growth and progression." (PMID 31366407, 2019). "The cell densities of certain subtypes of T cells, such as CD3+ T cells, CD8+ T cells and FOXP3+ regulatory T cells (Tregs), determine their immunoactive and immunosuppressive effects on the tumor microenvironment." (PMID 31464648, 2019). "Tumor‐infiltrating Foxp3 + Treg was positively correlated with tumor‐infiltrating DC2s (r2 = 0.772; P < .001)." (PMID 31631566, 2019). "Tumor-infiltrating Tregs in B-cell lymphoma are memory T cells that often express the forkhead box transcription factor FOXP3, a master gene involved in the regulation of the Treg cell lineage and a specific Treg marker." (PMID 30999581, 2019). "Of note, there was a trend towards a lower intratumoral CD8+ to FOXP3+ ratio in BRCA2-mutated tumors that needs to be carefully interpreted, but suggests a more suppressed tumor immune microenvironment." (PMID 31549213, 2019). "We found that variable numbers of Tregs, identified with FoxP3 nuclear positivity, were present both in the IM and CT in each tumour." (PMID 31358801, 2019). "First of all, we found a positive correlation of FoxP3+ Treg recruitment between the two compartments, suggesting that Treg cells can proportionally infiltrated into the tumor." (PMID 30781400, 2019). "Further studies are necessary to confirm the correlation between clinical efficacy of PD-1/PD-L1 antibodies and the density of CD4+ T cells and Foxp3+ Treg cells in the tumor microenvironment." (PMID 30978241, 2019). "In contrast, the presence of Treg (CD4+CD25+FOXP3+T cells), a subset of CD4+ T cells, appears to cause tumor immunosuppression, especially in most solid tumors." (PMID 31118034, 2019). "Examination of CT-2A-dmEGFRvIII-Luc and SMA560-dmEGFRvIII-Luc tumors established the expression of inhibitory receptors PD-1 and FoxP3 on T cells and inhibitory ligand PD-L1 on tumor cells." (PMID 31142380, 2019). "Exercised wild-type had 17% slower growth rate, 24% longer survival, and 2-fold tumor-CD+ 8/FoxP3+ ratio than sedentary controls." (PMID 31164094, 2019).
tumor (continued). "We observed that the frequency of CD4+Foxp3+ Tregs was significantly increased in the populations of circuiting and tumor-infiltrating T cells from BC patients compared with those from healthy donors, as demonstrated by flow cytometry (P < 0.05)." (PMID 30718502, 2019). "A high frequency of tumor-infiltrating FOXP3+ Tregs was often significantly negatively correlated with patient survival." (PMID 31174544, 2019). "Various studies have reported that an increased FoxP3+ Tregs infiltration in tumor specimens correlates with worse prognosis in cervical cancer." (PMID 31337018, 2019). "Multivariate analysis revealed that FoxP3+ Treg stromal infiltration, tumor stage and histological grade independently influenced patient prognosis." (PMID 30781400, 2019). "Transcriptomic and flow cytometry analyses demonstrate that ST2 expression induces a more activated and migratory phenotype in FOXP3+ Tregs, which favors their accumulation in the tumor environment." (PMID 31165767, 2019). "Our results indicated a significant reduction in the population of CD25 + FOXP3 + cells in the tumor tissues of Py-treated mice compared to those of the control mice (P < 0.001)." (PMID 30979375, 2019). "FoxP3+ Treg infiltration in both compartments was also evaluated according to patient clinical data, such as gender, tumor localization, tumor stage, tumor histological grade, tumor invasion and tumor risk factors." (PMID 30781400, 2019). "Further to assess the effect of the DTT-neoAg vaccination on cellular immune composition of TILs, we measured the percentage of NK cells in the tumor tissues and FoxP3+/CD4+ ratio in the TILs." (PMID 31749795, 2019). "FOXP3 is a well known marker of Tregs, with a pivotal role in the development and differentiation of these cells to promote tumour immune escape." (PMID 31381571, 2019). "Based on these studies and our own data we propose that these CD8+FoxP3+ T cells likely represent tumor-specific effector T cells, recruited to the tumor sites, rather than suppressive Tregs." (PMID 30755279, 2019). "We observed a significant decrease in the incidence of CD4+FoxP3+T cells in treated tumor tissue (F = 7.567, DF = 5, by ANOVA with Sidak’s posttest; p < 0.0001)." (PMID 31462642, 2019). "Here microenvironmental conditions where FOXP3 acts as a tumor suppressor or an oncogene should be clearly determined in specific cancers in association with TRL4, NFAT and NF-κB signaling in the future." (PMID 31815635, 2019). "CD8-positive cells were frequently detected, infiltrating all but one tumor, whereas FOXP3-positive cells were found in 16 out of 30 tumor sections." (PMID 30879106, 2019). "First, we compared the capacity of isolated tumor-infiltrating ST2+ versus ST2− CD4+ FOXP3+ Tregs to suppress CD4+ responder T cells from naive St2−/− donor mice in vitro." (PMID 31165767, 2019). "When looking at other T-cell populations in PCa, studies have noted high proportions of both CD4+ and CD8+ forkhead box P3 (Foxp3+) regulatory T cells (Tregs), within the tumor margin and epithelial compartment in PCa." (PMID 30984182, 2019). "In qRT-PCR, CCL20 mRNA expression in tumor tissues was significantly greater than in NATs (P = .01) and FOXP3 mRNA expression in tumor tissues was also significantly greater than in NATs (P = .02)." (PMID 31852159, 2019). "FoxP3 and RORγt mRNA was only found to be expressed in 11 tumor tissues and seven peritumor tissues." (PMID 30988066, 2019). "It is well documented that FOXP3 modulates Treg development and functions by immune evasion of tumor cells through imbalance of immunoediting and immunosurveillance in some cancers." (PMID 31815635, 2019). "We further demonstrated that the level of S1P1 was increased in tumor tissues from BC patients with a higher frequency of tumor-infiltrating CD4+Foxp3+ Tregs than in those from BC patients with a lower frequency of tumor-infiltrating CD4+Foxp3+ Tregs (n = 3)." (PMID 30718502, 2019).
tumor (continued). "PD-L1 expression and CD8+/FOXP3 Treg TILs ratios in tumor tissue have been correlated with prognosis across cancer types, giving support to a holistic approach to determining tumor microenvironment status as a prognostic factor." (PMID 31640798, 2019). "Combined treatment with the new developed CXCR4 antagonist, Pep R, plus anti-PD-1, reduced tumor-growth in two syngeneic murine models, anti-PD-1 sensitive and resistant, potentiating Granzyme and reducing Foxp3 cells infiltration." (PMID 31661001, 2019). "The patient with NSCLC who achieved PR had the highest CD8/FoxP3 ratio and proportion of 4-1BB/CD137+ cells in the IM, coupled with the lowest CD8/FoxP3 ratio throughout the tumor itself." (PMID 31801624, 2019). "These inconsistent prognostic correlations of FOXP3+ Tregs reflect the complexity of immune responses in tumor tissues." (PMID 31852159, 2019). "Intratumoral Tregs express CD4 and FoxP3 in both human and mouse and play a suppressive role in anti-tumor immunity." (PMID 31771616, 2019). "Multivariate analysis revealed that a high density of CD4+ T cells (P = 0.005; HR<0.001, 95% CI <0.001 to 0.28) and a high density of Foxp3+ cells (P = 0.003; HR<0.001, 95% CI NA) in tumor tissues were strongly correlated with better progression-free survival." (PMID 30978241, 2019). "Most of the tumor-infiltrating CD4+CD25+ cells expressed FoxP3, and their proportion was 2-fold higher in DC-specific Dll1−/− mice compared to wild-type littermates." (PMID 30940183, 2019). "A recent study in stage I lung carcinoma has unveiled the role that PDPN+ CAFs have in attenuating anti-tumor immunity by decreasing the CD8/Foxp3 T cell ration, supporting monocyte recruitment and their differentiation into TAMs." (PMID 31462327, 2019). "We also did not see differences in the density of infiltration of cytotoxic (CD8+) or regulatory (FoxP3+) T cells in either the tumor or stromal cell compartments." (PMID 31892360, 2019). "As frequencies of ST2+ CD4+ FOXP3+ Tregs in CRC tissue correlated with tumor scores, we next performed a transcriptomic analysis to better understand the role of ST2 for Treg function during intestinal tumorigenesis." (PMID 31165767, 2019). "FOXP3 plays an important role in Treg cells which leads to the suppression of cytotoxic T cells attacking tumor cells." (PMID 30761122, 2019). "CD4+ T helper, CD8+ CTLs, NK cells, M1 macrophages, and DCs are likely protecting against tumour growth whilst the CD4+ FOXP3+ Th2 cells, M2 macrophages, and myeloid-derived suppressor cells (MDSCs) simulate tumour growth." (PMID 31527531, 2019). "The data showed that FOXO1, CEBPB, and FOXP3 expression in tumor tissues from CRC patients with chemoresistance was dramatically higher than that in chemosensitive tumor tissues." (PMID 31395078, 2019). "This form of tumor-induced FOXP3+ Treg elevation represents a potential obstacle for cancer immunotherapy." (PMID 31852159, 2019). "Recently, an increasing number of studies have shown that FoxP3 is also expressed in cancer cells and plays vital roles in tumor progression." (PMID 31864387, 2019). "Further statistical analysis based on IHC suggested a significant positive correlation between FoxP3+ Tregs number and Lgr5 expression in tumor tissues (P < 0.0001; 9.77 ± 5.23 vs. 5.20 ± 4.50)." (PMID 31417548, 2019). "Conversely, inactivated CD8+CD25− and CD4+CD25+FOXP3+ Treg cells were found within the tumor tissue." (PMID 30987226, 2019). "Fifteen studies have examined the tumor infiltration of Foxp3 Tregs according to HPV status, including 7 that were focused on oropharyngeal SCC." (PMID 31510065, 2019). "Analysis of the immune infiltrate pleaded in favor of an improvement of the local immune tonus (as indicated by an increase in the ratio of CD8+ CTL over Foxp3+ Tregs), as well as an increased production of IFNα by tumor-infiltrating T cells." (PMID 30940805, 2019).
tumor (continued). "By contrast, the number of FoxP3+ Tregs negatively correlated with total Th1 cytokines and the ratio of total Th1 cytokines to total Th2 cytokines in tumor tissues (R2 = 0.0963, P = 0.0051, and R2 = 0.1649, P = 0.0002, respectively)." (PMID 31417548, 2019). "It was also found that a higher percentage of tumor occupied by PTPRC+ cells was strongly associated with enhanced tumor-infiltration by Tbet+ cells and Foxp3+ cells." (PMID 31740624, 2019). "The relationship between the number of intratumor FoxP3+ Tregs and Lgr5 expression in tumor tissues was analyzed by IHC and IF." (PMID 31417548, 2019). "The percentage of CD4+FOXP3+ Treg cells from the tumor infiltrating lymphocytes (TILs) of CRC patients was obviously higher than that from paired PBMCs." (PMID 31395078, 2019). "Increased IL-10+ B cell numbers in tumor tissues can also be accompanied by increased numbers of CD4+CD25+/highCD127low/− and Foxp3+ Tregs9–12, which are independently associated with tumor progression or reduced patient survival." (PMID 31519915, 2019). "CD73 is expressed primarily by the cancer cells and the immune cells such as CD4+Foxp3+ regulatory T cells (Tregs), and myeloid-derived suppressor cells (MDSCs) that are recruited by the tumor." (PMID 30635578, 2019). "FOXP3+ T-reg cells are associated with poor prognosis in various cancers, and with EMT type tumor cells." (PMID 30867568, 2019). "Comparable numbers of CD4+, CD8+, FOXP3+ and GrB+ cells were observed at the tumor microenvironment in the 46 patients series." (PMID 31481738, 2019). "Next, we assessed if there was a correlation between the number of Foxp3+Tbet+ Tregs and the presence of a type 1-oriented tumor immune infiltrate." (PMID 30658697, 2019). "Increased secretion of TGF-β within the tumor microenvironment recruits Tregs via expression of FoxP3, which ultimately results in diminished cytotoxic T-lymphocytes." (PMID 31091744, 2019). "This study highlights hypoxia-induced tumor immunosuppression by TREM-1+ TAMs that attracts CCR6 + Foxp3 + Tregs, and TREM-1+ TAMs confers HCC resistance to Programmed cell death 1 ligand 1 (PD-L1) treatment." (PMID 31464625, 2019). "The previous study revealed that immune profile, such as tumor infiltrating lymphocytes (TILs) and FOXP3, on BC tissues has both predictive and prognostic values in BC11,12." (PMID 30814616, 2019). "We found that the methylation levels of Foxp3 promoter in intratumoral T-cells significantly decreased with the tumor grade (IV<III<II<I, p<0.05)." (PMID 31006654, 2019). "Recent findings highlight the importance of TNFR2 as a key regulator of activated natural FoxP3+ regulatory T cells (Tregs) in inflammatory conditions, such as acute graft-vs.-host disease (GvHD) and the tumor microenvironment." (PMID 31555271, 2019). "Due to the close relationship between Treg cells and tumours’ microenvironment, FOXP3 has been widely studied in CRC development and progression." (PMID 30621735, 2019). "A multi-color immunofluorescence analysis revealed that CD8, PD-1, and Foxp3 were co-localized in mouse tumor tissues, implying that CD8+ cells and Foxp3+ Treg cells spatially interact in the TME." (PMID 31801611, 2019). "The association between proangiogenic activity of some subpopulations of TILs, like FoxP3+, is rather due to the co-occurrence of the immunologic switch together with the progression of a tumor than its direct influence of TILs to angiogenesis." (PMID 30680411, 2019). "LRRC32, located in human chromosomal 11q13-14, has frequently been found to be amplified in tumor tissue, and its overexpression was found to promote Foxp3+ regulatory T cell activity, which in turn contributed to enhancing cancer progression and metastasis." (PMID 31781506, 2019). "Conversely, we observed a significant decrease in the percentage of tumor infiltrating Foxp3+ Treg cells among CD4+ population in anti-4-1BB/anti-CD73-treated mice, compared with anti-4-1BB-treated mice alone." (PMID 30635578, 2019).
tumor (continued). "Emerging evidence indicates that FOXP3 regulates Treg development and functions to induce the immune evasion of tumor cells through imbalance of immunoediting and immunosurveillance and." (PMID 31815635, 2019). "A double staining of CD8+ cytotoxic T cells (CTL) and FoxP3+ (Treg) was performed and the cell density was evaluated in the intraepithelial and stromal compartment of the tumor." (PMID 31546872, 2019). "An infiltration of tumor tissue with FoxP3+ lymphocytes positively correlated with vessel density although there was no significant impact on prognosis." (PMID 30680411, 2019). "This cellular effect, the suppression of FoxP3+ Treg cells recruitment into the tumor, is a novel finding and strongly implicates enhanced antitumor immunity as a means by which aerobic exercise can suppress tumor growth." (PMID 31164094, 2019). "The discovery of somatic mutations and epigenetic alterations has revealed a dual role for FOXP3 regarding cancer biology as it can act as an oncogene or a tumour suppressor gene (e.g. breast, cancer and prostate)." (PMID 30621735, 2019). "A fully automated monoplex IHC panel was performed on sequential formalin-fixed paraffin-embedded tumor sections to identify CD3+, CD8+, CD45RO+, FoxP3+, and PD-1+ immune cells, and PD-L1 expression by tumor/immune cells." (PMID 31998307, 2019). "In colorectal cancer patients undergoing resection, a high level of FoxP3+ Tregs specific for tumor antigens drives immunosuppression and correlates with tumor recurrence and relapse." (PMID 31134056, 2019). "In tumor tissue, the number of FoxP3+ Tregs was positively correlated with IL-6 expression and negatively correlated with IL-2 and TNF-α expression (R2 = 0.0720, P = 0.0161; R2 = 0.1030, P = 0.0037; and R2 = 0.0507, P = 0.0446, respectively)." (PMID 31417548, 2019). "This study revealed that the CD4+Foxp3+ Treg frequency is increased in both the peripheral blood and tumor biopsies from BC patients compared with healthy controls and is highest in BC tissues." (PMID 30718502, 2019). "This revealed an increase in the presence of inflammatory cells, particularly intratumoral CD8+ T cells and tumor infiltrating FOXP3+ regulatory T cells in CES2-positive CCAs (p = 0.046 each)." (PMID 30867471, 2019). "In our study, density of tumor‐infiltrating Foxp3 + Treg cells was positively correlated with tumor‐infiltrating DC2s." (PMID 31631566, 2019). "Decreased ratios of tumor-infiltrating CD8+ T-cells to FOXP3+ Treg cells were shown to correlate with poor prognosis." (PMID 31640798, 2019). "Here we show that aerobic exercise in the form of chronic endurance training suppresses tumor recruitment of FoxP3+ Treg cells thus enhancing antitumor immune efficiency." (PMID 31164094, 2019). "We then assessed the messenger RNA (mRNA) expression levels of Foxp3 in each tumor between the sham control and laparotomy groups." (PMID 30216450, 2019). "Our present study found that higher levels of Foxp3+Tregs were observed in peritumoral and tumoral tissues than that in normal tissue." (PMID 30936882, 2019). "Specimens from cohort 2 were subjected to immunohistochemical analysis for the following markers: CD3, CD4, CD8, FOXP3, and PD-1 on tumor infiltrating lymphocytes (TIL) and PD-L1 on tumor cells." (PMID 30616523, 2019). "The immune staining of tumor sections showed that some Foxp3+ cells are located in close proximity to cells expressing Gr-1." (PMID 32038621, 2019). "In conclusion, FoxP3+ Treg infiltration in tumor stroma, tumor stage and tumor histological grade are strong and independent prognostic markers in HNSCC." (PMID 30781400, 2019). "Although GARP offers an important protective role for the host in inflammation-driven pathological conditions, the tolerogenic FoxP3/GARP/TGF-β axis is a mediator of the immunosuppressive microenvironment that enhances tumor growth." (PMID 29458436, 2018).